NLRP3 (NLR family pyrin domain containing 3)
Diseases named in the same sentence as NLRP3 in open-access papers (continued):
Sharing a sentence is not in itself a finding about the gene and the disease.
COVID-19 (continued). "We therefore examined the expression of these inflammatory cytokines in SARS-CoV-2 infected lung tissues and found that the COVID-19 related inflammatory cytokines were significantly decreased in the infected lung tissues of Nlrp3-KO mice compared to C57BL/6J mice." (PMID 34979342, 2022). "SARS-CoV-2 might directly activate NLRP3 inflammasome, and dysregulated NLRP3 inflammasome activity has been attributed with severe forms of COVID-19 with tissue damage and relevant cytokine storm." (PMID 35047633, 2022). "In this study, we found that exosomes from COVID-19 patients stimulate NLRP3 inflammasome formation and IL-1β production in endothelial cells and may promote a systemic inflammatory response." (PMID 35587188, 2022). "The inflammasome (NLRP3, associated with IL-18 activation) was reported to be activated during SARS-CoV-2 infection and has been proposed as an indicator of COVID-19 disease severity, predicting the release of pro-inflammatory cytokines that lead to dysregulated immune responses and tissue damage." (PMID 36359755, 2022). "Targeting the NLRP3 Inflammasome and mitigating aberrant inflammatory responses may play an important role in severe COVID-19 and complications of SARS-CoV-2 infection." (PMID 36090995, 2022). "Furthermore, we summarize the so far elucidated ways of SARS-CoV-2 induced NLRP3 inflammasome formation leading to pyroptosis, which strongly contributes to COVID-19 pathology." (PMID 35626754, 2022). "Many reports hold that unregulated NLRP3 inflammasome activation may potentially contribute to the severity of COVID-19 and its aftermath." (PMID 35052628, 2022). "Although SARS-CoV-2 infection triggers activation of the NLRP3 inflammasome that results in tissue damage and severe COVID-19, it is unclear at present whether ORF3a is directly involved in activating the NLRP3 inflammasome." (PMID 35356515, 2022). "Thus, our results demonstrated for the first time that exosomes from COVID-19 plasma trigger NLRP3 inflammasome in endothelial cells of distant organs resulting in IL-1β secretion and inflammatory response." (PMID 35587188, 2022). "The information obtained from this study could be a valuable source of evidence to support the targeting of the NLRP3 inflammasome pathway in developing preventive strategies for COVID-19-related inflammation." (PMID 36142258, 2022). "In addition, metformin inhibits the expression of inflammatory signaling pathways, including NLRP3 inflammasome and NF-κB activated in COVID-19." (PMID 36355535, 2022). "Furthermore, several studies have revealed that the NOD-like receptor family, pyrin domain containing 3 (NLRP3) inflammasome, a multiprotein complex crucial for host defense, maintains a high level of activation in patients with COVID-19." (PMID 35566589, 2022). "Emerging evidence indicates that an NLRP3 inflammasome is formed in COVID-19 patients and may predict the disease trajectory." (PMID 34203190, 2021). "The SARS-CoV-2 S protein promotes NLRP3 inflammasome activation and IL-1β secretion in COVID-19 patient-derived macrophages, and stimulation of the S protein upregulates both IL-1β and TNF-α; however, TNF-α is secreted in an NLRP3 inflammasome-independent manner." (PMID 34360684, 2021). "Furthermore, COVID-19 patients were found to contain higher NLRP3 levels compared to control subjects." (PMID 33669011, 2021). "The present review briefly summarizes immune dysregulation and its consequences, the roles of different non-coding RNAs in regulating the NLRP3 inflammasome, distinct types of vectors for their delivery, and potential therapeutic targets of microRNA for treatment of COVID-19." (PMID 34944639, 2021). "In fact, the clinical efficacy of BTK inhibitors in GvHD and COVID-19, and the reported role of the NLRP3/IL-1 axis in these disease states lend support to the notion that BTK-inhibitor therapy for NLRP3 inhibition warrants further preclinical and clinical exploration." (PMID 33718366, 2021).
COVID-19 (continued). "We believe that the NLRP3 inflammasome might be one of the triggering factors of the cytokine storm during COVID-19." (PMID 34059091, 2021). "Our data indicate that inhibition of NLRP3 inflammasome can reduce “cytokine storm” and lung injury caused by SARS-CoV-2 infection, suggesting that NLRP3 inflammasome is a potential target for COVID-19 therapy." (PMID 34341353, 2021). "In addition, the presence of fatal NLRP3 inflammasome aggregates of COVID-19-induced pneumonia in lung supports the existence of biological relations between viral infection and cytokine release syndrome." (PMID 33923537, 2021). "However, it is sufficient to say that the sex-related overactivation of NLRP3 inflammasome increases overall mortality in male COVID-19 patients, and NLRP3 inflammasome is activated during coronavirus infection." (PMID 34150848, 2021). "Different NLRP3 inflammasome activating signals were respectively regulated by sex elements in varying degrees, thus leading to different degrees of inflammation and different types of symptoms in COVID-19 patients." (PMID 34150848, 2021). "Finally, the quercetin, as an anti-inflammatory, antioxidant, analgesic and NLRP3 inflammasome inhibitor compound, can be a potential treatment for severe inflammation, which is the main life-threatening condition in patients with COVID-19." (PMID 33509217, 2021). "In monocytes, SARS-CoV-2 infection activates the NLRP3 inflammasome, suggesting that NLRP3 could be a marker of disease severity and a possible therapeutic target for COVID-19." (PMID 34299201, 2021). "Elevated HMGB1, NLRP3 and IL-6 levels could be discriminative markers for COVID-19 headache and may have implications for prevention and also for other secondary headaches related to other systemic viral infections." (PMID 34384355, 2021). "Moreover, older adults possess higher levels of NLRP3 inflammasome and are prone to develop cytokine storms, thus elderly patient with COVID-19 have worse prognosis." (PMID 34150848, 2021). "Together, these studies suggest that modulating NLRP3 or IL-1R1 related inflammatory responses could be a successful therapy in COVID-19." (PMID 33916409, 2021). "Moreover, dysregulation of NLRP3 inflammasome activity was observed in patients with severe COVID-19." (PMID 34150848, 2021). "In addition, the NLRP3 inflammasome can trigger the cytokine storm in the COVID-19 inflammatory cascade." (PMID 34367186, 2021). "Drugs that have previously been approved by the US Food and Drug Administration or other human-used compounds that can effectively inhibit NLRP3 inflammasome could be a potential treatment in severe COVID-19 cases." (PMID 33509217, 2021). "While the role of NLRP2 is not specifically characterized in SARS-CoV-2 infection, NLRP2 has shown sex-biased expression in influenza infection, and another member of the same NOD-like receptor family, NLRP3, is involved in inducing pulmonary inflammation in COVID-19." (PMID 34895312, 2021). "It is hypothesized that dysregulated angiotensin system and NLRP3 inflammasome play a key role in trigeminal induction and headache symptom in COVID-19." (PMID 34384355, 2021). "Conversely, increased levels of NR3C1, an NLRP3 antagonist, decreased the COVID-19 severity." (PMID 33672738, 2021). "In conclusion, it may well be that NLRP3 inflammasome activation may turn out be the link between COVID-19 and migraine, hence making the investigation of the possible link between inflammation and migraine even more relevant." (PMID 34112082, 2021). "Together, inhibiting NLRP3 inflammasome could bring down the “cytokine storm” and lung injury during SARS-CoV-2 infection, indicating NLRP3 inflammasome could be a target for COVID-19 treatment." (PMID 34696490, 2021). "Therefore, the NLRP3 inflammasome in myeloid cells has been proposed as a biomarker of COVID-19 severity." (PMID 34360684, 2021).
COVID-19 (continued). "However, other studies illustrated that testosterone has a protective effect against COVID-19 severity through inhibition of inflammatory signaling pathways including NF-κB, NLRP3 inflammasomes, and p38MAPK." (PMID 34568081, 2021). "Other possible DAMPs that may be playing roles in COVID-19 include extracellular RNAs that can activate TLR3 and TLR7, as well as extracellular hemoglobin, which activates NLRP3 and is associated with coagulation dysregulation and microclotting." (PMID 33672738, 2021). "The increased levels of complement cascade components were found in COVID-19 patients, such as C5b-9, C4d and MASP2, indicating that NLRP3 inflammasome may be activated in COVID-19 patients in a complement cascade-dependent manner." (PMID 34150848, 2021). "The results suggest that NLRP3 inflammasome participates in the pathophysiology of COVID-19 indicating that NLRP3-activated molecules can used markers of disease severity and are also potential therapeutic target for COVID-19." (PMID 34960782, 2021). "Similarly, a recent study conducted on COVID-19 patients reveals the activation of the NLRP3 inflammasome." (PMID 33467177, 2021). "Thus, it is likely that the decline of NAD+ levels, aggravated by COVID-19, increases the activity of NLRP3 and triggers cytokine storms in COVID-19 patients; restoring normal NAD+ levels likely alleviates COVID-19 symptoms." (PMID 34204163, 2021). "RDV could inhibit the NLRP3 inflammasome activation specially in our research and may play a role in the treatment of COVID-19." (PMID 34093539, 2021). "In the lung, the NLRP3 inflammasome, Mo and myeloid cells were enriched in COVID-19 patients." (PMID 33782412, 2021). "Sex differences may directly affect the activation of NLRP3 inflammasome, impacting the severity of observed COVID-19 symptoms." (PMID 34150848, 2021). "The activation of NLRP3 inflammasome during COVID-19 could promote excessive release of inflammatory cytokines." (PMID 33912161, 2021). "Thus, several NLRP3 inhibitors are in pre-clinical or clinical trials for the treatment of COVID-19, as summarized by van den Berg and te Velde." (PMID 34564326, 2021). "Active NLRP3 was found in PBMCs and postmortem tissues from moderate and severe COVID-19 patients." (PMID 33613573, 2021). "Considering the pivotal function of NLRP3 inflammasome in COVID-19, hydroxychloroquine could possibly inhibit NLRP3 inflammasome-induced cytokine storms and cause less severe symptoms." (PMID 34150848, 2021). "NLRP3 signaling inhibition may be a potential mechanism of action for several anti-inflammatory drugs effective in COVID-19, such as colchicine." (PMID 34234112, 2021). "NLRP3-mediated inflammasome also played an important role in patients with severe COVID-19." (PMID 34440608, 2021). "TLR7 stimulation may induce IFN-regulated cytokines release and, interestingly, SARS-CoV-2, binding the TLR, may promote NLRP3 inflammasome activation, further inducing an inflammatory response and worsening the prognosis of COVID-19." (PMID 33633566, 2020). "The overproduction of TNF-α in COVID-19 may preferentially activate the NLRP3 inflammasome relative to other immunological pathways." (PMID 32655582, 2020). "This decline, exacerbated by COVID-19, might promote hyperactivation of NLRP3 and the trigger cytokine storms in COVID-19 patients." (PMID 32470948, 2020). "Importantly, the rapid progression to severe phenotypes in COVID-19 patients coincides with an abrupt shift from the NLRP3 cytokine storm to a compensatory immunosuppressive state." (PMID 33003552, 2020). "Low or absent levels of IFN I lead to the unchecked activation of NLRP3, further predisposing elder and obese patients to severe form of COVID-19." (PMID 33426541, 2020). "Furthermore, Colchicine has been successfully tested as inhibitor of NLRP3 inflammasome, improving survival outcomes in COVID-19 patients since it suppresses caspase-1 activation and subsequent IL-1β and IL-18 processing." (PMID 33193349, 2020).
COVID-19 (continued). "Thus, NLRP3 inflammasome and pyroptosis pathways are considered as attractive targets for therapy of COVID-19 with severe symptoms." (PMID 33584656, 2020). "Indeed, patients with a reduced immune capacity demonstrated a dysregulated NLRP3 inflammasome activity, which results in severe COVID-19 with tissue damage and a cytokine storm (van den Berg and te Velde, 2020)." (PMID 33584335, 2020). "In addition to activating the innate and adaptive immune system, IFN I suppression of NLRP3 is another therapeutic mechanism against COVID-19." (PMID 33426541, 2020). "AGEs may increase COVID-19 severity in the aged by inhibiting the NLRP3 inflammasome during the early stages of viral infection when the inflammatory program is activated by the SARS-CoV-1 3a protein." (PMID 32470948, 2020). "Moreover, in agreement with a recent study reporting that SREBP-2 is highly expressed in severe COVID-19 alongside NLRP3 activation, our data further support the idea that lipid and cholesterol synthesis are crucial processes in the pathology of many viral infections." (PMID 41471247, 2025). "By modulating NLRP3, vitamin D may counter the inflammatory pathology in COVID-19." (PMID 39406981, 2024). "Moreover, the specific contribution of NLRP3 inflammasome activation and IL-1 signaling to COVID-19 immunopathogenesis remains unclear." (PMID 39882243, 2024). "In COVID-19 patients, particularly those who experience severe infection or long COVID, the activation of the NLRP3 inflammasome may perpetuate this chronic inflammatory state, leading to immune exhaustion, neuroinflammation, and worsening of age-related conditions." (PMID 39720706, 2024). "The mechanisms by which vitamin D may impact COVID-19 pathogenesis include modulating inflammatory cytokine production, stimulating antimicrobial peptides, regulating the renin–angiotensin system, and tempering the NLRP3 inflammasome." (PMID 39406981, 2024). "Collectively, these data indicate that NLRP3 affects the disease progression in mice, supporting the hypothesis (and clinical findings) indicating that NLRP3 is critical for the genesis of severe inflammation observed in some lethal cases of COVID-19." (PMID 38838044, 2024). "Hence, we investigated whether VitD3 treatment can reduce the NLRP3 inflammasome pathway in a cohort of severe COVID-19 patients." (PMID 38748756, 2024). "Despite these limitations, our study highlights that the clinically observed effect of VitD3 treatment during COVID-19 could be due, at least in part, to its suppression of NLRP3 inflammasome pathway; hence supporting its potential use as a supplement to ameliorate COVID-19 severity." (PMID 38748756, 2024). "Additionally, using a cohort of COVD-19 patients with different disease severity status, the main inflammatory cytokine of the NLRP3 inflammasome pathway, IL-1β, was shown to be significantly upregulated in severe COVID-19 patients when compared to asymptomatic patients." (PMID 38748756, 2024). "Adding the IFN response, Renin-Angiotensin mechanism, and NLRP3 pathways from the C19DMap to an existing macrophage polarisation model helped elucidate the innate immune response that macrophages trigger upon acute COVID-19, in addition to highlighting their contribution to the disease’s pathology." (PMID 38414974, 2023). "Indeed, NLRP3 rs10157379 and rs10754558 are the ones positively related to severe COVID-19." (PMID 37360532, 2023). "In addition, this paper also listed other drugs that may treat COVID-19 by acting on the NLRP3 inflammasome." (PMID 37868953, 2023). "Therefore, target NLRP3 inflammasomes implicate a promising therapeutics to deal with COVID-19." (PMID 36960050, 2023). "Therefore, by inhibiting the NLRP3 inflammasome in COVID-19, Nrf2 activators may significantly decrease SARS-CoV-2 infection-induced inflammation." (PMID 37796433, 2023). "Moreover, NLRP3 inflammasome activation had an impact on the clinical outcome of COVID-19." (PMID 37251383, 2023).
COVID-19 (continued). "Also, elevated levels of NLRP3 inflammasome activation that serves as a platform for mature IL-1β release is directly related to hyperinflammation as well as increased disease severity of COVID-19 patients." (PMID 37799713, 2023). "SARS-CoV-2 infection could trigger the activation of NLRP3 inflammasome to release IL-1β, IL-18, and gasdermin D and, consequently, damage to lung tissue in patients with COVID-19, suggesting the dysregulation of NLRP3 inflammasome might contribute to the severity of COVID-19." (PMID 36960050, 2023). "Abnormal NLRP3 activation during acute infection may lead to pathological tissue injury and may underpin the exaggerated immune response, since it contributes to the cytokine storm in acute COVID-19." (PMID 36675440, 2023). "The NLRP3 inflammasome could be used as a prospective predictor of COVID-19 severity and outcomes." (PMID 37251383, 2023). "The shared LIFR leukemia inhibitory factor receptor (M151443) with immunoglobulin/cytokine domains and the NLRP3 (M606416) pyrin-like genes could be involved in the inflammatory response to COVID-19 as well as the enhanced inflammation from adrenergic stimulation in EDS and other conditions." (PMID 37504295, 2023). "It was reported that the NLRP3 inflammasome was over-activated in elderly patients with COVID-19, which could be attributable to defects in mitochondrial functioning, enhanced production of mitochondrial ROS (mtROS) and massive release of mitochondrial DNA (mtDNA)." (PMID 37251383, 2023). "Thus, quercetin acted as an NLRP3 inflammasome inhibitor and could be exploited to dampen severe inflammation in COVID-19 patients." (PMID 37251383, 2023). "Thus, it is reasonable to suggest that SARS-Cov-2 infection may participate in COVID-19-related myocarditis by activating the NLRP3 inflammasome." (PMID 37256114, 2023). "In addition, NLRP3 may be one of the reasons why COVID-19 is more likely to affect older people, as it manifests an increase of activity during the aging process." (PMID 36618363, 2022). "Therefore, Vestitol, Pachypodol and I-SPD in XFBD could effectively treat COVID-19 through NLRP3 and CSF2 and reduce the clinical symptoms of patients." (PMID 36034710, 2022). "This activation of NLRP3 by Sars-CoV-2 may support post-COVID-19 neurodegenerative diseases." (PMID 35966209, 2022). "Traditionally, activation of the NLRP3 inflammasone is regarded to be the main inducer of pathogenic pro-inflammatory cytokines IL-1β, IL-18 and IL-6 during COVID-19, but it has become clear that multiple non-conical pathways can contribute and indeed become the dominate inducers of IL-1β." (PMID 35244141, 2022). "Clinically, over-regulated or dysregulated NLRP3 inflammasome activation in SARS-CoV and SARS-CoV-2-infected patients could trigger a cytokine storm that causes tissue damage and organ failure in patients with severe SARS or COVID-19 leading to death." (PMID 35356515, 2022). "The NLRP3-mediated pyroptosis in microglia might explain COVID-19-driven neuroinflammation." (PMID 35626754, 2022). "Furthermore, NLRP3 inflammasome components were upregulated in COVID-19 patients compared to HC." (PMID 35327634, 2022). "In addition, a combination of NLRP3 inhibitors with other immunomodulators could be considered as promising therapeutics for treating COVID-19 patients with specific conditions, for example severe COVID-19 patients with prominent cytokine storm." (PMID 34979342, 2022). "Moreover, the introduction of LPS also activates similar signaling pathways, in particular the AT1R/JAK/STAT signaling pathway and the assembly of NLRP3 in the inflammasome in infected/damaged lung tissue cells and resident macrophages, which mimics moderate and severe COVID-19 pathology." (PMID 36290634, 2022). "Therefore, XFBD can effectively alleviate the clinical symptoms of COVID-19 through NLRP3 and CSF2." (PMID 36034710, 2022).